CD36 (CD36 molecule (CD36 blood group))
Diseases named in the same sentence as CD36 in open-access papers (continued):
Sharing a sentence is not in itself a finding about the gene and the disease.
keratitis (2 papers, 2022 to 2025). A corneal disease that is characterized by inflammation of the cornea. "Although involved in the sterile inflammation of the retina, CD36 is a key component of resistance to keratitis caused by infection with pathogenic agents such as Staphylococcus aureus." (PMID 36611964, 2022). "Herein, we describe the isolation of 16 Cm strains from the eyes of 10 CD36-knockout mice, a majority with keratitis, housed in an AAALAC-accredited vivarium." (PMID 39665562, 2025). "Three Corynebacterium mastitidis strains were cultured from the eyes of CD36-knockout mice (B6.129S1-Cd36tm1Mfe/J) with and without keratitis housed at a biomedical research institute." (PMID 39665562, 2025).
kidney inflammation (2 papers, 2020 to 2025). "By investigating multiple inflammatory mediators (CD93, CD36, STAT3, NF-Kappa B, and TLR2/4), our results highlight the therapeutic potential of hAAT in treating kidney inflammation." (PMID 40723823, 2025).
Latent infections (2 papers, 2019 to 2025). "Polymorphisms like rs1761667 that lower CD36 expression could thus alter PPARδ-driven lipid–immune crosstalk, affecting the host’s ability to control latent infection." (PMID 41410218, 2025). "CD36 and SR-B1 are involved in immune signalling pathways including host response to Mtb, escape mechanisms of Mtb from phagocytes and modulation of host immune defenses during latent infection." (PMID 41410218, 2025). "Given its involvement in both lipid metabolism and pathogen recognition, reduced CD36 expression due to rs1761667 may not only impair cytokine release but also alter intracellular lipid handling, potentially creating a microenvironment more favourable for latent infection." (PMID 41410218, 2025).
Lipedema (2 papers, 2020 to 2022). Disorder of adipose tissue characterized by symmetric and bilateral enlargement of the lower extremities due to abnormal deposition of subcutaneous fat often in obese women. "Adipocytes differentiated from lipedema ASCs-T and ASCs-A showed an increase in adiponectin, LPL and CD36 gene expression compared to the same cells from healthy ASCs." (PMID 32059474, 2020). "This is partly supported by data showing significant upregulation of various adipogenic genes, including PPARγ, CD36/fatty acid translocase, and the fatty acid binding protein-4 (FABP4) in in vitro differentiated lipedema adipocytes from non-obese donors compared to non-lipedema controls." (PMID 36675759, 2022).
liver cirrhosis (2 papers, 2023 to 2025). "Furthermore, Rgkl ameliorated liver cirrhosis by modulating LSEC metabolic functions via the CD36/PPAR/CPT-1 pathway and suppressing HSC activation through the RhoA/ROCK/YAP and PI3K/AKT/NF-κB pathways." (PMID 41039598, 2025).
meningioma (2 papers, 2025). A generally slow growing tumor attached to the dura mater. "Through scRNA-seq, we demonstrate that NOTCH3 + human meningioma cells exhibit enriched expression of CD36." (PMID 40502769, 2025). "The scRNA-seq data revealed a correlation between NOTCH3 + meningioma cells and clusters-of-differentiation 36 (CD36) expression, indicating that CD36 is enriched in NOTCH3 + cells." (PMID 40502769, 2025). "Furthermore, patient-derived primary meningioma lines stratified by NOTCH3 expression confirmed higher CD36 expression and increased maximal mitochondrial respiration in NOTCH3-high cells in the presence of palmitate, supporting enhanced FAO." (PMID 40502769, 2025). "We established NOTCH3 high and low patient-derived primary meningioma lines and validated NOTCH3 correlates with CD36 expression." (PMID 40502769, 2025).
myelodysplastic syndrome (2 papers, 2023 to 2025). A clonal hematopoietic disorder characterized by dysplasia and ineffective hematopoiesis in one or more of the hematopoietic cell lines. "DisGeNET data reveal associations between myelodysplastic syndrome and the genes CD36, DAB2, ENPEP, and TIMP1." (PMID 40565366, 2025).
nephrotic syndrome (2 papers, 2019 to 2024). A collection of symptoms that include severe edema, proteinuria, and hypoalbuminemia; it is indicative of renal dysfunction. "It is reported that in primary nephrotic syndrome mouse, the overexpression of CD36 in the podocyte promotes its apoptosis." (PMID 31592160, 2019).
neuroblastoma (2 papers, 2014 to 2021). Neuroblastoma (NB) is the most common solid, extracranial childhood tumor. "In this connection, we found that 24-OH and 27-OH, but also 7β-OH, induced expression of IL-8, MCP-1, β1-integrin, CD36, and MMP-9 in human neuroblastoma SH-SY5Y cells." (PMID 24802026, 2014).
non-alcoholic fatty liver (2 papers, 2012 to 2021). A benign form of fatty non-alcoholic fatty liver disease where the disease has not yet progressed to the inflammation of liver. "Therefore, Cd36 deficiency might contribute to the progression of non-alcoholic fatty liver to NASH, which is managed by inflammation and subsequent cytokine and chemokine production." (PMID 34850865, 2021).
osteoporosis (2 papers, 2020 to 2023). A condition of reduced bone mass, with decreased cortical thickness and a decrease in the number and size of the trabeculae of cancellous bone (but normal chemical composition), resulting in increased fracture incidence. "The significance of environmental factors in diseases has been shown by a subcellular proteomics study that identified four candidate osteoporosis-related molecules, namely P4HB (β subunit of prolyl 4-hydroxylase), CD36, β1 integrin, and actinin-1." (PMID 32927783, 2020).
papillary thyroid cancer (2 papers, 2025). "For instance, in papillary thyroid cancer, high expression of CD36 on macrophages increases the recurrence rate." (PMID 41465497, 2025).
polyposis (2 papers, 2018 to 2021). "We have previously reported tentative evidence that polymorphisms in CD36 influence the age at which polyposis expression occurs, based on a relatively small population of patients with confirmed APC pathogenic variants." (PMID 33926505, 2021). "If these results can be verified in an independent cohort of FAP patients additional clinical information will be required to determine the precise role of CD36 in ameliorating or promoting polyposis development." (PMID 30065793, 2018). "Three single nucleotide polymorphisms (SNPs); rs1049673, rs1761667 and rs1984112 in CD36, have been investigated in 275 FAP patients to determine if they were associated with age of polyposis or risk of developing disease." (PMID 30065793, 2018). "When the variant allele’s presence was considered an autosomal dominant modifier, a significant difference between the ages of polyposis presentation was observed, indicating the modifying effects of CD36 resulted in a later age of disease presentation within the MCR-FAP group." (PMID 33926505, 2021). "This is 13 year younger and 12 years older than the average age of polyposis in this sample cohort for patients with mutations in the MCR and AFAP region, which were 29 and 46 years of age respectively, before taking into account the CD36 SNP genotypes." (PMID 30065793, 2018). "Due to the standard procedure of colectomy it is almost impossible to obtain accurate information about the age of cancer diagnosis in this population and as such we are unable to determine whether CD36 variants are associated with cancer risk rather than the appearance of polyposis." (PMID 30065793, 2018).
prion disease (2 papers, 2010 to 2012). A transmissible disease that is caused by a protein that is able to induce abnormal folding of normal cellular proteins, leading to characteristic spongiform brain changes, which are associated with neuronal loss without an inflammatory response. "Conversely, the class B scavenger receptor, CD36, which is the scavenger receptor most consistently associated with phagocytosis of β-amyloid was only slightly increased during prion disease and was down-regulated upon LPS stimulation." (PMID 20878768, 2010). "Our findings provide new insights into the mechanisms underlying the activation of microglia by neurotoxic prion peptides and open perspectives for new therapeutic strategies for prion diseases by modulation of CD36 signaling." (PMID 22292032, 2012). "Although more studies are needed to confirm and explore these initial findings, our study identified a potential molecular target for the treatment of prion diseases and provides perspectives for new therapeutic strategies for prion diseases by modulation of CD36 signaling." (PMID 22292032, 2012).
schizophrenia (2 papers, 2018 to 2022). A major psychotic disorder characterized by abnormalities in the perception or expression of reality. "CD36 dysregulation may therefore be linked to immune abnormalities frequently observed in both peripheral tissues and the central nervous system of schizophrenia patients." (PMID 36310155, 2022). "Likewise, increased expression of CD36 in T helper cells in schizophrenia may be linked to metabolic abnormalities associated with the disease." (PMID 36310155, 2022). "Expression of three PBMC epitopes, monocyte GLUT1 and T helper cell CD36 and IR, was found to be significantly altered in schizophrenia." (PMID 36310155, 2022). "The identified biomarkers, T helper cell CD36 and monocyte GLUT1, showed significant predictive capability in both drug-naïve and medicated schizophrenia patients, as well as in a trans-diagnostic psychiatric patient cohort, suggesting their potential clinical relevance." (PMID 36310155, 2022). "A multivariable diagnostic model was built using the three significant biomarkers of schizophrenia identified in the patient vs. control comparison, i.e., monocyte GLUT1 and T helper cell IR and CD36, adjusted for cell counts." (PMID 36310155, 2022). "Therefore, further research is required to evaluate the connection between schizophrenia and GLUT1 and CD36 expression in monocytes and T helper cells." (PMID 36310155, 2022).
skin infection (2 papers, 2018 to 2020). An inflammatory process affecting the skin, caused by bacteria, viruses, parasites, or fungi. "In addition, CD36 expression on macrophages plays a significant role in host control of inflammation and skin damage during skin infection caused by S. aureus." (PMID 33426011, 2020). "Although CD36 is well-known for its functions in pathogens and apoptotic neutrophils clearance, and has been reported to be essential to control the host innate response to Staphylococcus aureus skin infections, negative regulation of CD36 by bacteria or bacterial toxins has not been investigated." (PMID 30233583, 2018).
soft tissue sarcoma (2 papers, 2019 to 2022). A malignant neoplasm arising from muscle tissue, adipose tissue, blood vessels, fibrous tissue, or other supportive tissues excluding the bones. "Drug targeting of CD36 demonstrated promising results for patients with advanced soft tissue sarcoma in the initial clinical trials." (PMID 36686729, 2022).
triglyceride deposit cardiomyovasculopathy (2 papers, 2022 to 2024). "These patients were asymptomatic in spite of maximum uptake scores, which suggested that they had some disorders in 123I-BMIPP uptake, such as CD36 deficiency or triglyceride deposit cardiomyovasculopathy (TGCV)." (PMID 38535135, 2024). "Third, 123I-BMIPP scintigraphy is also interrupted by certain illnesses, such as fatty acid translocase (FAT)/CD36 gene mutation or triglyceride deposit cardiomyovasculopathy (TGCV)." (PMID 36354869, 2022).
ulcerative colitis (2 papers, 2012 to 2019). An inflammatory bowel disease involving the mucosal surface of the large intestine and rectum. "Interestingly gene expression of PPAR-γ is down-regulated in the damaged mucosa of patients with ulcerative colitis which is in accordance with results in the present study showing a decrease in CD36 expression in damaged mucosa compared with non-damaged." (PMID 23119050, 2012).
urothelial carcinoma (2 papers, 2022 to 2025). A malignant neoplasm derived from the transitional epithelium of the urinary tract (urinary bladder, ureter, urethra, or renal pelvis). "Therefore, focus of the present research was to explore the relationship between immunohistochemical expression of TIPE2 and CD36 in urothelial carcinoma and clinicopathological findings and prognosis." (PMID 40060230, 2025). "To date, few studies have explored the impact of CD36 in urothelial carcinoma." (PMID 35159947, 2022).
angina (1 paper, 2025). "FFDS has demonstrated its potential in reducing circulating TG levels and angina frequency in patients with SCHD, which may be due to the active ingredients of FFDS acting on LPL, CD36, FABPpm, L-FABP, LCAT, and CEPT." (PMID 39944604, 2025).
anorexia nervosa (1 paper, 2016). A disorder most often seen in adolescent females characterized by a refusal to maintain a minimally normal body weight, an intense fear of gaining weight, a disturbance in body image, and, in postmenarcheal females, the development of amenorrhea. "Of those nine genes, AKAP6 and NTNG1 were genes associated with anorexia nervosa and the remaining seven (AGT, CD36, CD38, FOXP1, PPARA, PPARG and SELL) were selected for their relationship with T2D." (PMID 27483138, 2016).
aortic atherosclerosis (1 paper, 2021). A atherosclerosis that involves the aorta. "We further show that loss of EC CD36 led to reduced aortic atherosclerosis lesion in female mice." (PMID 34888367, 2021).
aortic valve disease (1 paper, 2022). "Therefore, the expression of CD36 and SR-BI in VECs might be crucial for lipid accumulation in the aortic valve during early-stage aortic valve disease." (PMID 36115863, 2022).
aortic valve stenosis (1 paper, 2024). Aortic valve stenosis (AVS) is a condition characterized by narrowing of the heart's aortic valve opening. "Interestingly, we found increased expression of CD36, which has been shown to be downregulated in aortic valve stenosis, in the VEC1 cluster." (PMID 39766890, 2024).
Arterial thrombosis (1 paper, 2025). The formation of a blood clot inside an artery. "This study establishes FcRγ as a first functional coreceptor for CD36 in platelets, which enables lipid platelet hyperactivity and arterial thrombosis." (PMID 40668626, 2025).
Asymmetric septal hypertrophy (1 paper, 2023). Hypertrophic cardiomyopathy with an asymmetrical pattern of hypertrophy, with a predilection for the interventricular septum and myocyte disarray. "Several studies reported a high prevalence of FAT/CD36 deficiency in patients with dilated, ischemic, or hypertrophic cardiomyopathy with asymmetric septal hypertrophy." (PMID 37233656, 2023).
Atrophy (1 paper, 2021). Any weakening or degeneration, especially through lack of use. "Deletion of Thbs1 effectors/receptors, including ATF6α, CD36 or CD47 does not diminish Thbs1-dependent cardiac atrophy." (PMID 34168130, 2021). "Taken together, these results indicate that Thbs1-mediated cardiac atrophy and premature lethality are independent of CD36 or CD47." (PMID 34168130, 2021).
bladder urothelial cancer (1 paper, 2025). "Using immunohistochemistry, 60 specimens of bladder urothelial cancer (UC) for the expression of TIPE2 and CD36 were studied and compared with the clinicopathologic parameters and survival data." (PMID 40060230, 2025).
bleeding disorders (1 paper, 2020). "Interestingly, CD36 deficiencies do not appear to increase the risk of bleeding disorders, and deficiencies in CD36 or pharmacological blocking of JNK kinases lead to less thrombotic events in hyperlipidemic mice." (PMID 33092021, 2020).
Bowen’s disease (1 paper, 2022). "In conflict with the previous findings, our study demonstrated that the CD36 serve as a tumor suppressor which was down-regulated in CSCC when compared with Bowen disease." (PMID 36085041, 2022). "Besides, the proteins of TNC, FSCN1, SERPINB1, ACTN1 and RAB31 in CSCC were significantly up-regulated, while COL3A1, COL1A1 and CD36 were significantly down-regulated relative to Bowen disease in proteomics results." (PMID 36085041, 2022). "And next, among 20 proteins, 8 proteins (TNC, FSCN1, SERPINB1, ACTN1, RAB31, COL3A1, COL1A1 and CD36) expressed levels showed significant differences between CSCC and Bowen disease." (PMID 36085041, 2022).
brain cancer (1 paper, 2024). A primary or metastatic malignant neoplasm affecting the brain. "Our analysis revealed that >59% of cases possessed gain of copy number of CD36, with Brain cancer and Kidney cancer the highest at 98%." (PMID 39627379, 2024). "In some indications, such as Brain cancer and Non-Small Cell Lung Cancer (NSCLC), the CD36/CD47 expression levels were positively correlated with disease progression." (PMID 39627379, 2024).
brain tumors (1 paper, 2022). "In this context, in brain tumors with high percentage of CD36+ TIL-Treg cells, inhibition of mitochondrial FA-oxidation prevented Treg cell immunosuppression." (PMID 36352020, 2022).
celiac disease (1 paper, 2016). An autoimmune genetic disorder with an unknown pattern of inheritance that primarily affects the digestive tract. "Our data show down regulation of CD36 in celiac patients and the CD36 protein has also been previously shown to be significantly reduced in active as compared to inactive celiac disease and normal mucosal samples." (PMID 27483138, 2016).
cerebellar pilocytic astrocytoma (1 paper, 2013). A WHO Grade 1 astrocytoma which arises in the cerebellum. "Hypothalamo-chiasmatic pilocytic astrocytomas and cerebellar pilocytic astrocytomas have a distinctive gene signature and several differential expressed genes (ICAM1, CRK, CD36, and IQGAP1) are targets for available drugs: fluvastatin and/or celecoxib." (PMID 24252689, 2013).
cerebral amyloid angiopathy (1 paper, 2025). "Notably, deletion of CD36 reduces cerebral amyloid angiopathy in amyloid precursor protein (APP)-overexpressing mice, likely by enhancing brain-to-blood clearance via endothelial CD36 rather than microglial mechanisms." (PMID 41301546, 2025).
cerebral aneurysms (1 paper, 2023). "Our findings suggest a future role for plasma CD36 and GSH assays in attempting to identify cerebral aneurysms before rupture." (PMID 38196515, 2023).
cerebrovascular diseases (1 paper, 2021). "CD36 pathway may be an underlying cause of CVDs and cerebrovascular diseases." (PMID 34368262, 2021).
chronic granulomatous disease (1 paper, 2024). Chronic granulomatous disease (CGD) is a rare primary immunodeficiency, mainly affecting phagocytes, which is characterized by an increased susceptibility to severe and recurrent bacterial and fungal infections, along with the development of granulomas. "Another study demonstrated a similar trend in chronic granulomatous disease (CGD), in which disease progression was promoted by NOX2-producing mo-macs lacking the MHCII+CD206+CD36+ mature phenotype." (PMID 38352879, 2024).
chronic headache (1 paper, 2022). "The effects of high dietary omega-3 and low omega-6 targeted alteration to treat migraine in the parent randomized clinical trial suggested that the binding of long chain fatty acid to CD36 might play vital roles in chronic headache and possibly for migraine." (PMID 35896985, 2022).
cognitive decline (1 paper, 2022). "Additional mutations in CD36 associated with certain traits characteristic of the cognitive decline in AD have also been found." (PMID 35768560, 2022).
colorectal adenoma (1 paper, 2019). An adenoma that arises from the colon or rectum. "In the present work, we found that CD36 was commonly downregulated in human CRC, and revealed a progressive loss of CD36 from colorectal adenomas to carcinomas, which may be due to high methylation levels and polymorphism of CD36 in CRC46,47." (PMID 31484922, 2019). "In conclusion, we found epithelial loss of CD36 expression occurred early in human colorectal adenomas and was extensively absent in primary carcinomas, and decreased CD36 level was strongly associated with malignant properties of CRC cells." (PMID 31484922, 2019).